IL1B (interleukin 1 beta)
Diseases named in the same sentence as IL1B in open-access papers (continued):
Sharing a sentence is not in itself a finding about the gene and the disease.
endolymphatic hydrops (1 paper, 2024). An accumulation of endolymph in the inner ear (labyrinth) leading to buildup of pressure and distortion of intralabyrinthine structures, such as cochlea and semicircular canals. "Our previous research demonstrated that IL-1β maturation and release can trigger cell pyroptosis, exacerbating the severity of the endolymphatic hydrops in a mouse model; however, the specific mechanism through which IL-1β influences MD symptoms remains unclear." (PMID 39567494, 2024).
epidermoid cysts (1 paper, 2024). "Mice lacking the IL-1 receptor (IL-1R) (IL1r−/−) or deficient in IL1-β developed immunosuppression and multiple epidermal cysts after chronic UVB, suggesting that induced somatic events and an altered innate immune response may be involved in the initiation of epidermoid cysts." (PMID 39456581, 2024).
epididymitis (1 paper, 2023). Inflammation of the epididymis. "In the vivo experiments, levels of the proinflammatory cytokines IL-1α, IL-6, IL-17A, TNF-α, IL-1β, MCP-1, and GM-CSF, mRNA for MyD88 related genes, and the percentages of monocyte-derived DCs (Mo-DCs) were significantly elevated in mice with epididymitis." (PMID 37175545, 2023).
epithelial ovarian tumors (1 paper, 2023). "Recent studies have suggested that tumor necrosis factor-α (TNF-α) promotes the expression of pro-inflammatory cytokines (IL-1β, IL-6 and TNF-α) in human epithelial ovarian tumors." (PMID 37305383, 2023).
erysipelas (1 paper, 2017). An infection of the upper layers of the skin caused by species of streptococcus. "Our results show that increased serum IL1-β level in erysipelas patients is the T allele of SOD2 SNP C2734T dependent." (PMID 28512644, 2017). "This assumption is supported by our observation that serum IL-1β levels were higher in erysipelas patients homozygous for T allele than in patients with the heterozygous form." (PMID 28512644, 2017). "Therefore, we believe that serum levels of IL-1β could serve as a surrogate marker for predisposition to erysipelas and impaired antioxydase system." (PMID 28512644, 2017). "Although IL-1β level was elevated in the serum of erysipelas with T/T genotype as compared to the controls, differences in IL-1β levels were not significant between the acute and convalescent phases in the patients." (PMID 28512644, 2017).
Erythema nodosum (1 paper, 2013). An erythematous eruption commonly associated with drug reactions or infection and characterized by inflammatory nodules that are usually tender, multiple, and bilateral. "The authors demonstrated that the IL-1b +3962 gene polymorphism seems to be associated with the presence of erythema nodosum in patients with BD." (PMID 23559861, 2013).
erythroderma (1 paper, 2023). "The findings showed an atypical expression of IL-1B and IL-18 that was verified in the skin of SS patients but not in the EI group, indicating that it may not be related to an erythroderma condition." (PMID 36902104, 2023).
eumycetoma (1 paper, 2019). "In conclusion, this study indicates that both IL-35 and IL-37 are negatively associated with the levels of IL-1β and IL-12 in eumycetoma mycetoma infection; and high levels of IL-37 and IL-35 may have a negative impact on disease progression." (PMID 30946748, 2019). "Data of the current study clearly showed the serum levels of IL-1β and IL-12 in eumycetoma patients with different lesion size and disease duration were positively correlated with each other, and negatively correlated with IL-35 and IL-37." (PMID 30946748, 2019). "Our data showed that eumycetoma patients presented higher circulating levels of IL-1β, IL-12, IL-37 and IL-35 compared to controls." (PMID 30946748, 2019).
extrapulmonary tuberculosis (1 paper, 2010). A tuberculosis that occurs at body sites other than the lung. "In single locus association tests, interleukin (IL)-1β +3953 C/T was associated with extrapulmonary tuberculosis compared to PPD+ controls (P = 0.049)." (PMID 20196868, 2010). "In this pilot study among extrapulmonary tuberculosis patients with well-characterized immune defects, genetic variants in IL-1β, VDR Fok1, and TLR2 were associated with an increased risk of extrapulmonary disease." (PMID 20196868, 2010). "The results of this study suggest that an evaluation of the underlying mechanism(s) of the genetic variants in IL-1β +3953, VDR Fok1 A/G, and the TLR2 microsatellite--and their role in the pathogenesis of extrapulmonary tuberculosis--is warranted." (PMID 20196868, 2010).
Fanconi anemia complementation group C (1 paper, 2017). Fanconi anemia caused by mutations of the FANCC gene. "FANCC (fanconi anemia complementation group C) has been shown to modulate TLR and p38 MAPK-dependent expression of IL-1β in macrophages." (PMID 28539126, 2017).
fasciolosis (1 paper, 2019). "A similar phenomenon might be possible during fasciolosis, since FhCL3 expressed by the juvenile worm could induce IL-1β, while FhHDM-1 secreted in all the stages would control the function of the inflammasome." (PMID 30967874, 2019).
female infertility (1 paper, 2020). Diminished or absent ability of a female to achieve conception. "489TT/HHV-6A positive women also showed higher levels of IL-1β, IL-1α, and IL-8 (CXCL8) suggesting that the 489TT gain-of-function variant not only favors virus entry but also triggers a wide inflammatory response that might contribute to female infertility." (PMID 32153407, 2020).
femoral neck fracture (1 paper, 2022). Fractures of the short, constricted portion of the thigh bone between the femur head and the trochanters. "Hip chondrocytes from patients with OA or femoral neck fracture (non-OA) were stimulated with IL-1β, TNF, forskolin and opioid peptides." (PMID 35740371, 2022).
fibroblast disorder (1 paper, 2017). "Further investigations on the mechanism underlying caspase-1-regulated pyroptosis and IL-18/IL-1β-regulated fibroblast disorder are required to elucidate the function of NLRP3 inflammasome in DCM." (PMID 28790925, 2017).
ganglioglioma (1 paper, 2012). A well differentiated, slow growing neuroepithelial neoplasm composed of neoplastic, mature ganglion cells and neoplastic glial cells. "Accordingly, high expression of IL-1β has also been reported in tumor astrocytes in ganglioglioma, which represent a well-known cause of chronic intractable epilepsy." (PMID 23270518, 2012).
Gastric Metaplasia (1 paper, 2013). Intestinal metaplasia of the gastric mucosa is an intermediate precancerous gastric lesion in the gastric cancer cascade from chronic gastritis and atrophy to dysplasia and adenocarcinoma. "Given that IL-1β induces gastric metaplasia and stimulates expression of the proto-oncogene IL-6 in various cell types, we hypothesized that IL-1β induces expansion of the SPEM phenotype by stimulating proliferation and IL-6 expression along with phosphorylation of STAT-3 (pSTAT-3)." (PMID 23520544, 2013).
Gastrointestinal dysmotility (1 paper, 2017). Abnormal intestinal contractions, such as spasms and intestinal paralysis, related to the loss of the ability of the gut to coordinate muscular activity because of endogenous or exogenous causes. "To investigate whether the gastrointestinal dysmotility and the neuroplastic changes of the ENS were associated with an inflammatory process triggered by HSV-1 exposure, we evaluated the gut level of two relevant pro-inflammatory cytokines (TNF-α and IL-1β) using ELISA." (PMID 28732069, 2017).
GI inflammation (1 paper, 2022). "Studies have revealed that the main characteristics of CAP-induced GI inflammation in mice are elevated levels of inflammatory cytokines, especially IL-10, IL-1β, and TNF-α." (PMID 35267319, 2022).
giant cell arteritis (1 paper, 2022). "Macrophages also contribute to the pathology of age-related diseases, such as polymyalgia rheumatic (PMR) and giant cell arteritis (GCA), which only occur in people over 50 years old and are both characterized by increasing production of IL-1β and IL-6 by arterial macrophages." (PMID 35625939, 2022).
Gilbert syndrome (1 paper, 2021). An autosomal recessive inherited disorder characterized by unconjugated hyperbilirubinemia, resulting in harmless intermittent jaundice. "One possible explanation for this positive association is that unconjugated bilirubin might affect the immune response by downregulating intracellular production of cytokines, as evident from the decreased IL-6 and IL-1β level in monocytes from individuals with Gilbert's Syndrome." (PMID 34603596, 2021). "Second, the NHANES database does not collect data on unconjugated bilirubin, Gilbert's Syndrome, and cytokines level, such as IL-6 and IL-1β." (PMID 34603596, 2021).
GM1 gangliosidosis (1 paper, 2023). A rare lysosomal storage disorder characterized biochemically by deficient beta-galactosidase activity and clinically by a wide range of variable neurovisceral, ophthalmological and dysmorphic features. "The brains of Glb1−/− and Glb1+/− mouse models of GM1 gangliosidosis have shown activated subsets of Mφs and microglial cells and the massive production of IL1β and TNFα." (PMID 37189685, 2023).
GNE myopathy (1 paper, 2013). "Protein expression was analyzed by serial staining of sections from biopsies of all GNE myopathy patients with immunohistochemical double labeling of 1) APP and MHC-I, 2) αB-crystallin and NCAM, 3) IL-1β and β-amyloid, and 4) iNOS and P-neurofilament." (PMID 23496965, 2013).
growth deficiency (1 paper, 2021). "Conversely, we can presume that fetal malnutrition and growth deficiency in the course of FGR may be a consequence of decreasing IL1B (log2FC = −5.11) expression." (PMID 33923632, 2021).
hemangioma (1 paper, 2016). A benign vascular lesion characterized by the formation of capillary-sized or cavernous vascular channels. "However, IL-6, IL-1β, and IFN-β protein levels in the three clinical samples with hemangiomas were dramatically increased compared to the healthy samples." (PMID 27252695, 2016).
hemophilia (1 paper, 2020). Hemophilia is a genetic disorder characterized by spontaneous hemorrhage or prolonged bleeding due to factor VIII or IX deficiency. "Consistently confirming the involvement of IL-1β in the pathophysiology of HA, some authors documented markedly elevated IL-1β levels in histological section of the synovial membranes collected during synovectomy or joint replacement from HA patients as compared to patients without hemophilia." (PMID 32581836, 2020).
hemorrhagic disease (1 paper, 2018). Spontaneous or near spontaneous bleeding caused by a defect in clotting mechanisms (blood coagulation disorders) or another abnormality causing a structural flaw in the blood vessels (hemostatic disorders). "Consistent with hemorrhagic disease, negative control animals showed signs of liver damage as evidenced by increased levels of liver enzyme AST, and several key cytokines such as IL-1β, IL-6, IL-1Ra, MIP-1α, TNFα, IFN-γ, IL-2, and FGF-β." (PMID 30723475, 2018).
hepatobiliary tumors (1 paper, 2025). "Some randomized trials have tested probiotics in hepatobiliary tumors and have shown an increase in TNFα and IL1β in the postoperative period, supporting the use of probiotics to modulate the immune response and reduce infectious complications in patients." (PMID 40310432, 2025).
hepatotoxicity (1 paper, 2018). Toxicity that causes injury to the liver or impairs the liver function. "IL-1β-511CT and -511TT genotypes among alcohol users increased the risk of severe hepatotoxicity (42.9% versus 40.7%, OR = 1.64, 95% CI: 0.10–51.13, P = 0.84 and 42.9% versus 37.0%, OR = 1.80, 95% CI: 0.11–56.75, P = 0.90, resp)." (PMID 29849489, 2018). "Similarly, IL-1β-511TT genotype among alcohol users increased the risk for the development ARV-associated hepatotoxicity in HIV-infected individuals (OR = 2.64, P = 0.19)." (PMID 29849489, 2018). "IL-1β-511TT genotype among combined nevirapine and alcohol users increased the risk for the development of ARV-associated hepatotoxicity in HIV-infected individuals (OR = 2.84, P = 0.24)." (PMID 29849489, 2018). "Similarly, IL-1β-511CT and -511 TT genotypes and alcohol usage showed increased risk to develop ARV-associated hepatotoxicity (48.8% versus 45.9%, OR = 2.29, 95% CI: 0.61–9.28, P = 0.27 and 41.9% versus 34.1%, OR = 2.64, 95% CI: 0.68–11.06, P = 0.19, resp)." (PMID 29849489, 2018).
heroin addicts (1 paper, 2021). "The analysis revealed that the levels of IL-1ra, IL-1β, IL-5, IL-12p70, IL-13, IL-15, MIP-1β, bFGF, and RANTES in the plasma of heroin addicts in the AW and PW stages were not significantly different from those in the plasma of the control group subjects (data not shown)." (PMID 34489980, 2021).
hippocampal atrophy (1 paper, 2024). "TNFα and IL-1β signaling may represent a more chronic component of stress that contributes to hippocampal atrophy." (PMID 39595087, 2024).
HIVinfection (1 paper, 2008). "Increased cytokine levels in semen have been established in HIVinfection (IL-1β), and genital infectionssuch as Chlamydia trachomatis (IL-8) and Neisseriagonorrhoeae (IL-6, IL-8)." (PMID 18615190, 2008).
homeostasis (1 paper, 2021). "A previous study demonstrated that IL-1β, IL-6, and TGF-β promotes the differentiation of naive T cells into Th17 cells and in turn suppresses Treg differentiation, leading to homeostasis disorders." (PMID 33575330, 2021).
hydrarthrosis (1 paper, 2015). Accumulation of watery fluid in the cavity of a joint. "We found that the Kampo medicine boiogito attenuated hydrarthrosis and joint pain and decreased IL-1β in the articular cavity in rats with surgically induced OA." (PMID 26703073, 2015). "Boiogito appears to alleviate hydrarthrosis by suppressing articular pro-inflammatory cytokine IL-1β production and inhibiting water transport through AQPs in the synovium." (PMID 26703073, 2015). "Administration of boiogito improved hydrarthrosis, IL-1β, and HA concentrations and alleviated knee joint pain in rats with OA." (PMID 26703073, 2015). "Indomethacin reduced IL-1β and knee joint pain but failed to improve hydrarthrosis or HA concentration in rats with OA." (PMID 26703073, 2015).
hypertensive heart disease (1 paper, 2021). Abnormal enlargement of the heart resulting from long-standing hypertension. "The findings of the PPI network indicated that IL-6, TNF, IL-1β, and NFKBIA were predicted as the main genes of AS-IV against hypertensive heart disease and the KEGG pathways analysis showed that TNF signaling pathway was its key pathway." (PMID 34803698, 2021). "Our findings indicated that the targeted genes of AS-IV against hypertensive heart disease are involved in oxidative stress and inflammation, including SOD2, SOD1, IL-6, TNF, and IL-1β." (PMID 34803698, 2021).
hypertensive nephropathy (1 paper, 2016). Kidney damage that results from chronically elevated blood pressure; complications include glomerular damage resulting in proteinuria and hematuria. "Cytokines IL-1β, IL-6, and TNF-α play a significant role in the occurrence and development of hypertensive nephropathy." (PMID 27069492, 2016).
idiopathic panuveitis (1 paper, 2022). "IL-1β acts locally like an amplification signal in the pathological process associated with chronic inflammation as show previously in the vitreous from patients with idiopathic panuveitis." (PMID 35061677, 2022).
immune thrombocytopenia (1 paper, 2021). "Meanwhile, the complement-IL-1β loop could cause impairment of mesenchymal stem cells, leading to immune thrombocytopenia." (PMID 33767707, 2021).
infectious peritonitis (1 paper, 2012). Inflammation of the peritoneum due to infection by bacteria or fungi. "In the effluent from patients with infectious peritonitis, as compared with uninfected patients, increased levels of various pro-inflammatory cytokines were found, including IL-1β, IL-8, TNFα, IL-6, and IFNγ." (PMID 22481867, 2012). "PMφ from CAPD patients collected during infectious peritonitis, showed a marked increase in the secretion of TNFα and IL-1β as compared with macrophages from infection free patients, when they were stimulated ex vivo with LPS." (PMID 22481867, 2012). "Pro-IL-1β processing and secretion rather than synthesis proves to be increased in pMφ from infectious peritonitis suggesting up-regulation of caspase-1 in vivo." (PMID 22481867, 2012).
infective endocarditis (1 paper, 2025). Infective endocarditis (IE) is an infection of the inner lining of the heart chambers (endocardium) and valves. "The observed cytokine patterns are relevant to G. adiacens pathogenesis, given the roles of IL-8 and IL-1β in infective endocarditis and oral infections." (PMID 41440315, 2025).
inflammatory breast carcinoma (1 paper, 2025). An advanced, invasive breast adenocarcinoma characterized by the presence of distinct changes in the overlying skin. "A previous study demonstrated that in inflammatory breast cancer, decreasing NF-κβ significantly suppresses the expressions of IL-1β and IL-6." (PMID 40035822, 2025).
internalizing disorder (1 paper, 2022). A type of mental or behavioral disorder, typically in children and young adults, with symptoms including depression, anxiety and withdrawal. "There is no robust association of IL-1β levels and pediatric internalizing disorders or symptom severity based on review of the literature." (PMID 35880170, 2022).
Interstitial pneumonitis (1 paper, 2021). "Together our results reveal the potential ability of gefitinib to initiate sterile inflammation via two distinct mechanisms, and identified IL-1β and HMGB1 as key determinants of gefitinib-induced inflammation that may provide insights into gefitinib-induced interstitial pneumonitis." (PMID 33414419, 2021).
intestinal polyp (1 paper, 2022). Discrete abnormal tissue masses that protrude into the lumen of the intestine. "The administration of a 2% curcumin diet decreased the total number of intestinal polyps by 75% and reduced IL-1β, IL-6 and TNF-α protein expression." (PMID 36547085, 2022).
ischemic colitis (1 paper, 2020). Inflammation of the colon due to colonic ischemia resulting from alterations in systemic circulation or local vasculature. "Induction of ischemic colitis increased TNF-α, IL-1β, and IL-6 expressions, whereas decreased adenosine A2A receptor expression (P < 0.05)." (PMID 32149087, 2020). "Induction of ischemic colitis increased the expressions of inflammatory proteins, such as COX-2 (70–72 kDa), TNF-α (17 kDa), IL-1β (17 kDa), and IL-6 (22–27 kDa) in the colonic tissue (P < 0.05)." (PMID 32149087, 2020). "Expressions of inflammatory cytokines (TNF-α, IL-1β, and IL-6) and inflammatory mediator (COX-2) were upregulated in the ischemic colitis rats." (PMID 32149087, 2020). "In the present study, treatment with PDRN effectively suppressed ischemic colitis-induced COX-2, TNF-α, IL-1β, and IL-6 expressions in the colonic tissues." (PMID 32149087, 2020). "In the case of PDRN + DMPX treatment, TNF-α, IL-1β, and IL-6 levels were not changed compared to ischemic colitis-induced group." (PMID 32149087, 2020).
ischemic disease (1 paper, 2022). Lack of blood supply to an area of the body, resulting in impairment of tissue oxygenation. "In addition, BA can alleviate oxygen-glucose-deprived challenged microglia injury in ischemic diseases by attenuating expression of inflammatory cytokines TNF-α, IL-1β, IL-6, and IL-8 through TLR4 pathway." (PMID 36408278, 2022).
juvenile myelomonocytic leukemia (1 paper, 2021). A myelodysplastic/myeloproliferative neoplasm of childhood that is characterized by proliferation principally of the granulocytic and monocytic lineages. "Supporting this, they found increased caspase-1 activation and IL-1β production in CMML, juvenile myelomonocytic leukemia (JMML) and AML patients with KRAS mutations as compared to patients without KRAS mutations." (PMID 35155452, 2021).
kidney toxicity (1 paper, 2021). "APAP mediated kidney toxicity also encourages inflammatory cytokine interleukin (IL-1β, 6)." (PMID 33679180, 2021).